ENO1 (enolase 1)
Diseases named in the same sentence as ENO1 in open-access papers (continued):
Sharing a sentence is not in itself a finding about the gene and the disease.
thyroid cancer (8 papers, 2011 to 2025). "ENO1 is frequently overexpressed and is consistently linked to poor prognosis, advanced stage, and aggressive tumor features across multiple malignancies, including breast, lung, bladder, prostate, gastric, colorectal, pancreatic, and thyroid cancers." (PMID 41373732, 2025). "Our study demonstrated that ENO1 was an oncogene in thyroid carcinoma that acted downstream of mTOR/HIF1α and accelerated thyroid carcinoma progression via regulating CST1." (PMID 33968941, 2021). "Proliferation and migration of thyroid carcinoma cells were suppressed by depletion of ENO1; conversely, ENO1 overexpression promoted thyroid carcinoma cell growth and invasion." (PMID 33968941, 2021). "qRT-PCR and western blotting were also performed to confirm these results; there were higher ENO1 mRNA and protein levels in thyroid carcinoma samples." (PMID 33968941, 2021). "IHC staining showed that ENO1 was upregulated in thyroid carcinoma samples as compared with normal samples." (PMID 33968941, 2021). "In conclusion, we were the first to identify an oncogenic role of ENO1 in thyroid carcinoma; this will pave the way for a more efficient diagnosis and thyroid carcinoma therapy." (PMID 33968941, 2021). "In the present study, we found that the expression of ENO1 was upregulated in thyroid carcinoma samples." (PMID 33968941, 2021). "In the present study, we demonstrated that ENO1 plays an oncogenic role in thyroid carcinoma progression." (PMID 33968941, 2021). "Correlation of ENO1 expression with clinicopathological characteristics in 45 patients of thyroid carcinoma." (PMID 33968941, 2021). "Inversely, increased expression of S100A4 and ENO1 was correlated with increased proliferation and metastatic potential of thyroid carcinoma." (PMID 21835052, 2011). "Therefore, exploring the upstream regulator, the downstream effector and the role of ENO1 in thyroid carcinoma can help the oncologists gain more insights into molecular events during the development of thyroid carcinoma." (PMID 33968941, 2021). "We found upregulation of ENO1 in thyroid carcinoma compared with normal samples." (PMID 33968941, 2021). "Importantly, CST1 silencing reversed the oncogenic function of ENO1 on thyroid carcinoma cell growth, migration and tumorigenic capacity." (PMID 33968941, 2021). "In summary, although many complicated questions have not been answered, our study was the first to identify the mTOR/HIF1α/ENO1 pathway in thyroid carcinoma progression and ENO1 as a regulator of CST1, thereby paving the way for early diagnosis and efficient therapy of thyroid carcinoma." (PMID 33968941, 2021). "The expression of ENO1 in Normal tissue and thyroid carcinoma by IHC." (PMID 33968941, 2021). "Several studies demonstrate that α-Enolase (ENO1) participates in cancer development; nevertheless, the role of ENO1 in thyroid carcinoma progression remains unclear." (PMID 33968941, 2021). "Because ENO1 has been identified as an oncogene in several cancers, it could be a potential novel target for thyroid carcinoma." (PMID 33968941, 2021). "Therefore, enhanced glycolysis may be the reason why mTOR/HIF1α/ENO1 promotes thyroid carcinoma progression." (PMID 33968941, 2021). "Depletion of ENO1 suppressed TPC1 and BCPAP thyroid carcinoma cells’ proliferation to nearly half that of control cells." (PMID 33968941, 2021). "In this study, we presented the data that ENO1 positively regulated the expression of CST1 and CST4 in thyroid carcinoma cells." (PMID 33968941, 2021). "To further clarify the relationship between ENO1 and CST1 in thyroid carcinoma, we combined overexpression and knockdown assays in TPC1 cells." (PMID 33968941, 2021). "To study the function of ENO1 in thyroid carcinoma, we first analyzed the THCA database to determine the relevance of ENO1 in thyroid carcinoma." (PMID 33968941, 2021). "We demonstrated that ENO1 regulated CST1 expression and that these two proteins acted synergistically in thyroid carcinoma progression." (PMID 33968941, 2021).
thyroid cancer (continued). "Investigations performed on AUF1-depleted thyroid cancer cell lines revealed a cross-link between AUF1 and CD9, CD82, S100A4 and ENO1." (PMID 21835052, 2011). "ENO1 was related to carcinoma microclimate and positively interacted with cancer-related fibroblast infiltration in BRCA, esophageal cancer (ESCA), GBM, KICH, PAAD, and thyroid cancer." (PMID 39576845, 2024). "There was a positive correlation between ENO1 and CST1/CST4 in human thyroid carcinoma tissues." (PMID 33968941, 2021). "Nevertheless, the role of ENO1 in human thyroid carcinoma and its putative targets have not been investigated." (PMID 33968941, 2021).
triple-negative breast carcinoma (8 papers, 2021 to 2026). An invasive breast carcinoma which is negative for expression of estrogen receptor (ER), progesterone receptor (PR), and human epidermal growth factor receptor 2 (HER2). "A citrullinated peptide vaccine targeting ENO1 (citENO1 vaccine) in triple-negative breast cancer (TNBC) mouse models showed synergistic effects with PD-1 blockade, significantly inhibiting tumor growth and improving survival compared with controls." (PMID 41373732, 2025). "ENO1 clusters with overexpression of all the pathways involved in cancer hallmarks and epigenetic regulation in triple-negative breast carcinomas." (PMID 39483155, 2024). "Particularly, it has been characterized that ENO1 is overexpressed in triple-negative breast cancer (TNBC) samples." (PMID 39051682, 2024). "These novel data overall point to a potential role of ENO1 in recruiting immune pathways, particularly in triple-negative breast carcinomas and advanced disease, immediately suggesting that there may be a role for ENO1-targeted therapy as an adjunct to immune therapy." (PMID 39483155, 2024). "In triple-negative breast cancer (TNBC), knockdown of YBX1 inhibited the expression of glycolytic genes (ENO1, SLC2A6, LDHA, PFKP, PGAM1, and GPI) and downregulated the expression of EMT-related genes and tumor migration and invasion." (PMID 41507134, 2026). "Despite the fact that MDA-MB-231 cells are triple negative breast cancer cells and even the wild type cells are highly glycolytic, proteins critical to glycolysis, including ALDOA, ENO1 and G3P, were all significantly upregulated in the p300 KD cells." (PMID 34884992, 2021).
Alzheimer disease (7 papers, 2018 to 2025). A progressive, neurodegenerative disease characterized by loss of function and death of nerve cells in several areas of the brain leading to loss of cognitive function such as memory and language. "The expression of ENO1 was closely associated with many diseases, including Alzheimer's disease, diabetes, as well as cancers." (PMID 40586619, 2025). "According to the disease alliance terms, ENO1, CASP6, HSPD1, and CASP3 are associated with Alzheimer’s disease." (PMID 38107644, 2023). "Among the other screened hub proteins, ENO1, is reportedly involved in aging and age-related diseases, such as Alzheimer’s disease, while BCL2, belongs to an anti-apoptotic protein family." (PMID 29907735, 2018). "Elevated levels of PDCD5, ENO1, CHI3L1, PP3R1 and SCRN1 have been observed in CSF from individuals with Alzheimer disease." (PMID 36721240, 2023). "In addition, in the common carp liver, the KEGG pathway analysis showed that Alzheimer’s disease was related to genes INSR, GAPDHS, BAX, DHCR24, PPARG, ENO1, and VEGFA." (PMID 35741857, 2022).
Arthritis (7 papers, 2013 to 2024). Inflammation of a joint. "In contrast, other authors claimed that human and mouse citrullinated ENO1 are immunogenic while they may fail to induce arthritis even in genetic backgrounds susceptible to CIA." (PMID 26302382, 2015). "In this context, in 2015 we showed that prophylactic injection of ENO1 in a collagen-induced arthritis (CIA) mouse model allowed significant prevention of arthritis severity." (PMID 27025255, 2016). "In the DR4-IE-transgenic mice model, arthritis is induced by immunization by either the citrullinated or the native form of human ENO1 as well as of P. gingivalis ENO1." (PMID 26302382, 2015). "This study shows for the first time that, when injected in a prophylactic way in the CIA model, ENO1 has a dose-dependent inhibitory effect on arthritis severity, as assessed by different clinical, immunological and histological parameters." (PMID 26302382, 2015). "In the present study, we show that another enzyme of the glycolytic pathway, ENO1, has the ability to reduce arthritis severity in the CIA model when injected in a prophylactic way 24 hours before immunization with type II collagen." (PMID 26302382, 2015). "Since pEP1 is the immunodominant epitope of ENO1, we also assessed its influence on arthritis severity when injected prophylactically." (PMID 26302382, 2015). "ApoB may bind to enolase-1 expressed on the surface of immune cells to aggravate arthritis in RA patients." (PMID 34915859, 2021). "However, the SDN map identified five cSABPs (ENO1, FTL, IMMT, PDCD6IP and HSPA6) that were associated with various types of arthritis." (PMID 31511554, 2019). "Since prophylactic injections of ENO1 or pEP1 led to prevention of arthritis severity in the CIA model, one of the hypotheses was that this molecule has the ability to induce immunomodulatory cell populations." (PMID 26302382, 2015).
diabetes (7 papers, 2016 to 2025). "Four proteins were markedly under-expressed (Hsp60, HspA8, TUBA1A, and ENO1) and linked to the pathogenesis of diabetes or post-translationally modified by O-GlcNAc." (PMID 29867058, 2018). "This intronic miRNA is located in ENO1 that has been previously related to depression and diabetes." (PMID 32616021, 2020). "This same interaction could play a role in the effect of ENO1 on diabetes." (PMID 29867058, 2018). "The expression of Enolase 1, but not of other glycolytic enzymes, was increased in diabetes, whereas treatment of diabetic animals with dapagliflozin further increased the expression of Enolase 1, Aldolase B, and Pkm2." (PMID 36809274, 2023).
endometrial cancer (6 papers, 2015 to 2024). Primary or metastatic malignant neoplasm involving the endometrium (mucous membrane that lines the endometrial cavity). "However, the clinical significance of ENO1 expression remains unclear and its function and modulatory mechanisms have never been reported in endometrial carcinoma (EC)." (PMID 25951350, 2015).
esophageal cancer (6 papers, 2017 to 2024). A primary or metastatic malignant neoplasm involving the esophagus. "The study correlated local and circulating ENO1 protein levels in esophageal cancer (EC) with clinicopathological data, to assess its potential clinical value." (PMID 33628097, 2021). "Interestingly, plasma ENO1 levels decreased progressively in normal, precancerous condition of the esophagus and esophageal cancer, exactly in contrast to the tissue expression of the protein." (PMID 35836227, 2022). "However, ENO1 expression is more diversified in esophageal cancer than in others." (PMID 35610567, 2022).
Hepatic fibrosis (6 papers, 2013 to 2023). The presence of excessive fibrous connective tissue in the liver. "ENO1 as an autoantigen has been reported in systemic sclerosis (SSc)-associated interstitial lung disease and liver fibrosis evidenced as the frequent presence of anti-ENO1 autoantibodies in these patients." (PMID 37964270, 2023). "The results showed that, compared to HBV carriers, expression of enolase-1 was down regulated in the serum of patents with hepatic fibrosis, while expression of TSP-1 was up regulated in the serum of patients with hepatic fibrosis." (PMID 23845056, 2013). "The results indicated that TSP-1, TGF-β1, NF-κB, and enolase-1 likely play important roles in the process of hepatic fibrosis." (PMID 23845056, 2013). "The expression level of enolase-1 (α-enolase) was decreased while the level of thrombospondin-1 (TSP-1) increased in the serum of patients with hepatic fibrosis by western blot." (PMID 23845056, 2013). "Our experimental results indicated that the expression level of enolase-1 in the serum of patients with HBV hepatic fibrosis was significantly higher than that in HBV carriers." (PMID 23845056, 2013). "In the present study, the results of the protein microarray showed that autoantibodies to CENPF, ACY1, ENO1, and HSPA6 may have underlying detection values for liver fibrosis staging." (PMID 35059422, 2021). "Moreover, ENO1 was described as a serum biomarker in hepatic fibrosis, which provides additional evidence that this protein is crucial for organ injury and repair responses." (PMID 26035385, 2015). "Its change of concentration in the blood may reflect the degree of hepatic fibrosis suggesting that enolase-1 can be used as a serum marker for the prediction of hepatic fibrosis." (PMID 23845056, 2013). "Enolase-1 was at least 5.09-fold down-regulated in hepatic fibrosis patients compared to HBV carriers and TSP-1 was at least 7.56-fold up-regulated in hepatic fibrosis patients compared to HBV carriers." (PMID 23845056, 2013). "Enolase-1 and TSP-1 were detected in eight cases (four hepatic fibrosis patients and four HBV carriers)." (PMID 23845056, 2013). "Although the levels of enolase-1 and TSP-1 in the serum of HBV carriers and hepatic fibrosis patients can be detected, the relationship between the degree of liver fibrosis and their expression needs further study." (PMID 23845056, 2013). "The two proteins, enolase-1 and thrombospondin-1(TSP-1) were detected by western blot in the serum of hepatic fibrosis patients and HBV carriers." (PMID 23845056, 2013). "Enolase-1 and TSP-1 may be useful as biomarkers for the clinic diagnosis of hepatic fibrosis, but further study is necessary." (PMID 23845056, 2013). "Our study suggests enolase-1 and TSP-1 play important roles in the development of hepatic fibrosis." (PMID 23845056, 2013). "However there are no reports about enolase-1 and hepatic fibrosis." (PMID 23845056, 2013).
Hyperglycemia (6 papers, 2019 to 2023). An increased concentration of glucose in the blood. "KMT5A associated with RFX1 to modulate ENO1, thus involved in hyperglycemia-mediated EndMT in glomeruli of DN." (PMID 34803485, 2021). "Highly starchy food causes hyperglycemia and hyperinsulinemia, which increases oxidative stress and inflammatory responses, and can also lead to gastric carcinogenesis by upregulating glycolysis-related genes (enolase 1)." (PMID 33921757, 2021). "The levels of H4K20me1, a downstream target of KMT5A, decreased in hyperglycemia-treated HUVECs and the levels of H4K20me1 were enriched in the promoter region of enolase 1 (ENO1), regulating the ENO1 levels and thereby inducing EndMT." (PMID 36983082, 2023). "The present study demonstrated that hyperglycemia, via upregulation of ENO1 levels, participated in EndMT and vascular endothelial cells damage, thus mediating the genesis and development of DN." (PMID 34803485, 2021). "Collectively, these data implied that hyperglycemia/ENO1 induced GC malignant phenotype at least partially by modulating the TGF-β/Smad signaling pathway." (PMID 31889896, 2019). "We observed, possibly for the first time, that the expression of ENO1 was significantly higher in the hyperglycemia groups than the normal glucose group." (PMID 31889896, 2019). "Mechanistically, further research revealed that Snail‐mediated EMT played a vital role in the hyperglycemia/ENO1‐induced GC malignant phenotype." (PMID 31889896, 2019). "Our results indicated that hyperglycemia induced ENO1 expression to trigger Snail-induced EMT via the TGF-β/Smad signaling pathway in GC." (PMID 31889896, 2019). "In this study, we propose that hyperglycemia promotes the progression of EMT via activating ENO1 expression in GC." (PMID 31889896, 2019). "Together, our present findings indicated that hyperglycemia promoted GC cell proliferation, migration and invasion, as well as ENO1 expression." (PMID 31889896, 2019). "Mechanistically, the Western blot results analysis showed that ENO1 knockdown suppressed hyperglycemia-induced decreases in E-cadherin and increases in N-cadherin, Vimentin and Snail." (PMID 31889896, 2019). "ENO1 knockdown significantly weakened the GC cell proliferative capacity in both the normal glucose and hyperglycemia groups compared with the control groups." (PMID 31889896, 2019). "Previous study found ENO1 is involved in hyperglycemia-induced EMT." (PMID 34803485, 2021). "In this study, we speculate that KMT5A may regulate ENO1 levels, thus participating in hyperglycemia-induced EndMT in vascular endothelium." (PMID 34803485, 2021). "In the present study, we speculated KMT5A regulates ENO1 transcript, thus participating in hyperglycemia-induced EndMT in glomeruli of DN." (PMID 34803485, 2021). "In addition, to the best of our knowledge, very few studies have evaluated the effect of hyperglycemia on the expression of ENO1." (PMID 31889896, 2019). "All the results were consistent with our hypothesis that hyperglycemia-induced ENO1 overexpression promotes a malignant phenotype in GC via Snail-induced EMT through the TGF-β/Smad signaling pathway." (PMID 31889896, 2019). "Snail-induced EMT was promoted by hyperglycemia, and suppressed by ENO1 silencing." (PMID 31889896, 2019). "Notably, knockdown of ENO1 could significantly reverse the hyperglycemia-induced GC malignant phenotype." (PMID 31889896, 2019). "The ENO1 gene expression was lower (p < 0.001) and CS (p < 0.05) was higher in cells with the 1BR.3.N WWOX OE in comparison to control in hypoxia hyperglycemia." (PMID 35328751, 2022). "Further research confirmed that ENO1 knockdown significantly inhibited the TGF-β/Smad signaling pathway in both the normal glucose and hyperglycemia groups." (PMID 31889896, 2019). "In our study, we found that hyperglycemia promoted GC cell proliferation, migration, invasion and EMT, as well as ENO1 expression." (PMID 31889896, 2019).
Hyperglycemia (continued). "Our results revealed that the expression levels of TGF-β, phosphorylated-Smad2 (p-Smad2) and phosphorylated-Smad3 (p-Smad3) were decreased with ENO1 knockdown, whereas the total Smad2 and Smad3 expression levels were not significantly different between the normal glucose and hyperglycemia groups." (PMID 31889896, 2019). "However, whether ENO1 is also involved in hyperglycemia-induced EndMT is still not studied." (PMID 34803485, 2021).
leukaemia (6 papers, 2013 to 2024). "However, there are limited data on the presence or significance of ENO1 autoantibodies in haematological malignancies, particularly leukaemias and myelodysplastic neoplasms." (PMID 38473245, 2024).